TNFRSF4 (TNF receptor superfamily member 4)
Description:
Receptor for TNFSF4/OX40L/GP34. Is a costimulatory molecule implicated in long-term T-cell immunity. (Microbial infection) Acts as a receptor for human herpesvirus 6B/HHV-6B.
Synonyms: CD134; TXGP1L; ACT35; OX40; IMD16
Tractability: Antibody: a drug acting on it is in phase 2 or 3 trials; its Gene Ontology location is reachable by antibodies, with high confidence; UniProt predicts a signal peptide or a membrane-spanning region. Other modalities: a drug acting on it is in phase 2 or 3 trials.
Target class: Membrane receptor
Gene: Protein-coding gene on chromosome 1 (1,211,326 to 1,214,153, reverse strand). Ensembl gene ENSG00000186827.
Subcellular location: Membrane
Pathways (Reactome):
Immune System: TNFs bind their physiological receptors
Gene Ontology:
Molecular function: protein binding; tumor necrosis factor receptor activity
Biological process: immune response; inflammatory response; negative regulation of transcription by RNA polymerase II; positive regulation of B cell proliferation; positive regulation of immunoglobulin production; T cell proliferation; tumor necrosis factor-mediated signaling pathway
Cellular component: cell surface; external side of plasma membrane; plasma membrane; membrane
Genetic constraint (gnomAD): Loss-of-function variants: 21 observed, 20.29 expected, observed/expected ratio (o/e) 1.04, 90% interval 0.73 to 1.49. The synonymous counts are far from expectation, so gnomAD's model fits this gene poorly and the ratio says little. Missense variants: 408 observed, 327.3 expected, observed/expected ratio (o/e) 1.25, 90% interval 1.15 to 1.35. Synonymous variants: 197 observed, 145.4 expected, observed/expected ratio (o/e) 1.35, 90% interval 1.21 to 1.52.
Gene-disease validity (ClinGen):
ClinGen rates the evidence that TNFRSF4 causes each of these diseases.
combined immunodeficiency due to OX40 deficiency (autosomal recessive): Limited. Combined immunodeficiency due to OX40 deficiency is a rare combined T and B cell immunodeficiency characterized by susceptibility to develop an aggressive, childhood-onset, disseminated, cutaneous and systemic Kaposi sarcoma.
Homologues: Orthologues: chimpanzee TNFRSF4 (90% identical), macaque TNFRSF4 (77% identical), pig TNFRSF4 (65% identical), dog TNFRSF4 (64% identical), mouse Tnfrsf4 (61% identical), rat Tnfrsf4 (61% identical), guinea pig TNFRSF4 (55% identical), zebrafish tnfrsf11a (18% identical), zebrafish tnfrsf1b (18% identical), zebrafish hdr (17% identical), zebrafish cd40 (15% identical), zebrafish tnfrsfa (13% identical). Paralogues in human: TNFRSF1B (27% identical), TNFRSF8 (23% identical), LTBR (21% identical), TNFRSF11A (21% identical), TNFRSF6B (21% identical), TNFRSF21 (20% identical), NGFR (20% identical), TNFRSF18 (18% identical), CD40 (18% identical), RELT (17% identical), TNFRSF11B (17% identical), TNFRSF1A (17% identical), and 9 more.
Diseases named in the same sentence as TNFRSF4 in open-access papers:
TNFRSF4 is named in the same sentence as 244 diseases in open-access papers, as found by Europe PMC text mining. Sharing a sentence is not in itself a finding about the gene and the disease. The quoted sentences say what the papers report.
melanoma (64 papers, 2013 to 2025). A malignant, usually aggressive tumor composed of atypical, neoplastic melanocytes. "-TNFRSF4 was recognized as a gene that is implicated in the process of tumor suppression. - Decrease in the expression of TNFRSF4 in melanoma tissues from older individuals, while its level appears to be elevated in the younger age group." (PMID 38590525, 2024). "In other cancers, including melanoma, carcinomas and breast cancer, the expression of TNFRSF4 in the lymph nodes has been previously assessed." (PMID 38809883, 2024). "The TNFRSF4 expression was observed to be lower expressed in the older of melanoma tissues, and higher in the younger age group (P = 0.02)." (PMID 36100891, 2022). "TNFRSF4 expression was observed to be lower expressed in the older of melanoma tissues, and higher in the younger age group (P = 0.02)." (PMID 36100891, 2022). "For example, the expression of TNFRSF4 on TILs was correlated with favorable prognosis in human cancers, including advanced gastric cancer, non-small cell lung cancer, ovarian carcinoma, malignant melanoma, and colorectal cancer." (PMID 35562682, 2022). "The expression of TNFRSF4 on tumor-infiltrating lymphocytes (TILs) has been studied in different tumor types, such as breast cancer, melanoma, B-cell lymphoma and head and neck cancers." (PMID 34133324, 2021). "The TNFRSF4 molecule has been identified as a co-stimulatory agent that may significantly promote effective antitumoral responses in sarcoma, melanoma, and breast cancer, as suggested by preclinical research." (PMID 38590525, 2024). "We tested the TNFRSF4 protein levels by IHC in 14 melanoma tissue samples." (PMID 36100891, 2022). "The preclinical and clinical data indicated that melanoma treatment may move forward using agonists like OX40 (CD134, TNFRSF4), CD137, CD40, GITR, and CD27 activating co-stimulatory pathways." (PMID 34804979, 2021). "TNFRSF4, also known as OX40, activates the PI3K/PKB, NF-κB1 and NFAT pathways and enhances T cell-mediated antitumor immunity, thereby improving survival in several preclinical cancer models, including B16 melanoma and lung cancer." (PMID 36817422, 2023). "We tested the TNFRSF4 protein levels by IHC and examined the protein expression in 14 melanoma samples where the normal control slides showed a negative detection of TNFRSF4 protein." (PMID 36100891, 2022).
breast cancer (54 papers, 2013 to 2025). A primary or metastatic malignant neoplasm involving the breast. "Breast cancer associated TREG cells show a significantly higher expression of CTLA-4 and tumor necrosis factor receptor superfamily, member 4 (TNFRSF-4, also known as OX-40) on their membranes compared to other CD4+ and CD8+ T cells." (PMID 33467084, 2021). "The high level of co-expression of TNFRSF4 and CCL5 in the METABRIC data set suggests that either gene is associated with immune infiltration in breast cancer tumors." (PMID 34226941, 2021). "There are very few studies on serum TNFRSF4 and its role in MBC, with studies showing that the levels of TNFRSF4 are elevated in patients with breast cancer, but to our knowledge, no studies have been published on serum levels of TNFRSF4 and association with survival in MBC patients." (PMID 36945037, 2023).
autoimmune disease (33 papers, 2005 to 2025). A disorder resulting from loss of function or tissue destruction of an organ or multiple organs, arising from humoral or cellular immune responses of the individual to their own tissue constituents. "CD4T1 and CD4T10 included genes for costimulatory molecules OX40 (TNFRSF4) and GITR (TNFRSF18), both of which have been described to promote survival and proliferation of CD4+ Teff and have been targets of autoimmune disease therapeutics." (PMID 38743491, 2024). "OX40, which is also known as tumor necrosis factor receptor superfamily member 4 (TNFRSF4), and its ligand (OX40L) play a critical role in the pathogenesis of autoimmune diseases." (PMID 30944836, 2019).
COVID-19 (25 papers, 2021 to 2025). A disease caused by infection with severe acute respiratory syndrome coronavirus 2. "CD27, TNFRSF14, TNFRS18, and TNFRSF4 were highly expressed in the HLA_DR+ Tregs from severe COVID-19 patients." (PMID 40114921, 2025). "Common hubs in the RNA inflammation networks based on the four groups of COVID-19 severity included TOLLIP (toll-interacting protein) and TNFRSF4 (tumour necrosis factor receptor superfamily member 4)." (PMID 40362649, 2025). "This suggests that TOLLIP, TNFRSF4, AGER, and GHRL are crucial inflammatory COVID-19 markers." (PMID 40362649, 2025).
Autoimmunity (24 papers, 2005 to 2025). The occurrence of an immune reaction against the organism's own cells or tissues. "Accumulating data suggest that the interaction between TNFSF4 and its receptor, TNFRSF4, not only plays crucial roles in the induction of anti-tumor immunity, allergies and autoimmunity, but also suppresses the development of adaptive T regulatory (TR1) cells." (PMID 29285231, 2017).
lupus (22 papers, 2010 to 2025). "It had been reported that polymorphism characteristic of TNFRSF4 was related to systemic lupus erythematosus and Sjogren's syndrome." (PMID 36148160, 2022).
colorectal cancer (19 papers, 2015 to 2025). A primary or metastatic malignant neoplasm that affects the colon or rectum. "While these prognostic trends conflict with the trends observed in our model, several studies have also found that elevated expression of TNFRSF4 and its protein counterpart OX40 as favourable in cancers, including colorectal cancer (CRC), cutaneous malignant melanoma and endometrial carcinoma (EC)." (PMID 38809883, 2024).
glioma (18 papers, 2015 to 2025). A benign or malignant brain and spinal cord tumor that arises from glial cells (astrocytes, oligodendrocytes, ependymal cells). "The agonist OX40 (TNFRSF4) immunotherapy combined with vaccination reversed T lymphocyte exhaustion and prolonged survival in the glioma mouse model." (PMID 35000592, 2022). "However, according to clinicaltrials.gov portal, almost no studies are reported for OX40 (TNFRSF4) related molecules in pancreas cancers, prostate cancers, pheochromocytoma cancers, testis cancer, thymoma, glioma, thyroid cancers nor in adrenocortical cancers." (PMID 36224560, 2022).
ovarian carcinoma (18 papers, 2014 to 2025). A malignant neoplasm originating from the surface ovarian epithelium. "Moreover, patients with high TNFSF10 expression usually exhibited a good response to chemotherapy, while TNFRSF4 was associated with chemosensitivity and good prognosis in ovarian cancer patients, and IRF7 was upregulated in patients in the chemotherapy responsive group." (PMID 36590751, 2022). "Approximately three-fourths of ovarian cancer cases exhibit metastasis to the peritoneal cavity, and the TNFRSF4 fusion protein mCTH-ANXA5 is used in the treatment of metastatic ovarian cancer." (PMID 34367975, 2021). "Additionally, the combination of anti-CD73, anti-TNFRSF4, and mCTH-ANXA5 mAbs can be used to significantly improve the survival rate (12–24 days for all murine objects) and to reduce the burden of metastatic ovarian cancer by enhancing the function of cytotoxic T cells." (PMID 34367975, 2021).
atherosclerosis (15 papers, 2011 to 2025). A disease characterized by the build-up of fatty material and calcium deposition in the arterial wall resulting in partial or complete occlusion of the arterial lumen. "The TNFSF4/TNFRSF4 system, along with several other receptor-ligand pairs, is involved in the recruitment and activation of T-cells and is therefore tentatively implicated in atherosclerosis and acute coronary syndromes." (PMID 21445270, 2011). "The TNFSF4/TNFRSF4 system, along with several other receptor-ligand pairs, has been suggested to be involved in the recruitment and activation of T-cells and is therefore tentatively implicated in atherosclerosis and acute coronary syndromes such as MI." (PMID 21445270, 2011). "TNFRSF4 is involved in atherosclerosis development and tPA is involved in thrombolysis, while PRSS8, FRalpha, MIA, FUR, CDH3 and HE4 are involved in various cancer processes." (PMID 33066363, 2020). "Further support for a role of TNFSF4 in atherosclerosis was obtained in a study where blockage of the TNFSF4/TNFRSF4 interaction reduced lesion formation in low-density lipoprotein (LDL) receptor-deficient mice." (PMID 21445270, 2011). "The receptor/ligand interactions play a central role in atherosclerosis, hence TNFSF4 / TNFRSF4 interaction/interrupt can be used as a new treatment method for atherosclerosis." (PMID 30797237, 2019).
lung carcinoma (14 papers, 2016 to 2023). "Besides, TEDC2 expression was also correlated with TNFRSF25, TNFRSF4 and TNFRSF18 in our analysis, which might be correlated with immune evasion and poor outcome in lung cancer, but the molecular mechanisms of these immune checkpoint molecules still remain elusive and need further investigation." (PMID 36973475, 2023).
hepatocellular carcinoma (12 papers, 2017 to 2024). A malignant tumor that arises from hepatocytes. "We found that ITM2A, LTB, TNFRSF4, and TNFRSF18 were significantly overexpressed in hepatocellular carcinoma cell lines (Hep3B and Huh7) relative to normal liver cell lines (HL-7702)." (PMID 37006257, 2023).
colon carcinoma (11 papers, 2015 to 2025). "In colon cancer, the high expression of TNFRSF4 in TILs, mesenteric lymph nodes, or invasive margin lymphoid aggregates was reported to correlate with better overall survival." (PMID 34133324, 2021).
glioblastoma (10 papers, 2015 to 2025). The most malignant astrocytic tumor (WHO grade IV). "Similarly, the expression of TNFRSF4 was significantly higher (p < 0.001) in EMT-high samples of all cancer types, except for SKCM and Glioblastoma." (PMID 35096592, 2021).
lupus nephritis (10 papers, 2010 to 2022). Glomerulonephritis in the context of systemic lupus erythematosus. "But it observed TNFSF4 rather than TNFRSF4 expressed in a granular distribution predominantly along the epithelial side of the glomerular capillary wall, only in type IV lupus nephritis." (PMID 23936824, 2013).
malaria (9 papers, 2016 to 2025). Malaria is a serious and sometimes fatal disease caused by a parasite that commonly infects a certain type of mosquito which feeds on humans. "Evidence of malaria induced immunosuppression within our data was also observed in NK and γδ T cell subsets, where multiple co-inhibitory receptors were upregulated during infection (including TNFRSF4, TNFRSF9, TNFRSH18, HAVCR2, LAG3, and PDCD1)." (PMID 37968278, 2023).
sarcoma (9 papers, 2012 to 2024). A usually aggressive malignant neoplasm of the soft tissue or bone. "Using both our retrospective cohort of clinical samples, and data from The Cancer Genome Atlas (TCGA), we identify TNFRSF4/OX40 and TNFRSF9/4-1BB as two immune markers of potential relevance to sarcoma." (PMID 35558159, 2022). "OX40/TNFRSF4 and 4–1BB/TNFRSF9 were highly expressed in sarcoma subtypes versus other cancers." (PMID 35558159, 2022). "Analysis of the transcript levels of the costimulatory receptors OX40/TNFRSF4, ICOS, and GITR/TNFRSF18 indicated that ICOS and GITR transcripts were not highly expressed in any sarcoma subtype relative to other cancers in the TCGA dataset." (PMID 35558159, 2022).
type 1 diabetes (8 papers, 2014 to 2024). "While there have been no reports on the expression of TNFRSF4 in relation to Tregs in patients with type 1 diabetes, this has been reported to be significantly increased in patients with relapsed acute myeloid leukemia compared to healthy donors." (PMID 35626661, 2022).
neuroblastoma (6 papers, 2014 to 2024). Neuroblastoma (NB) is the most common solid, extracranial childhood tumor. "Taken together, these results clearly demonstrate that the low expression of TNFRSF4 observed in our cisplatin-resistant xenografts is significantly associated with poor prognostic indicators of neuroblastoma." (PMID 38809883, 2024). "Our study has identified the tumour necrosis factor receptor superfamily member 4 (TNFRSF4) gene as a marker of interest in neuroblastoma, particularly when looking at high-risk disease." (PMID 38809883, 2024). "Low TNFRSF4 expression correlated with poor prognostic indicators in neuroblastoma, such as age at diagnosis, stage, and risk stratification and significantly associated with reduced probability of both event-free and overall survival in neuroblastoma." (PMID 38809883, 2024). "We demonstrated that Low expression of TNFRSF4 was significantly associated with reduced probability of both event-free and overall survival in neuroblastoma and as such TNFRSF4 can be considered as an independent prognostic factor." (PMID 38809883, 2024). "The expression of TNFRSF4, which encodes the protein OX40, was assessed across different patient subgroups in large neuroblastoma cohorts to determine whether its expression could have prognostic value." (PMID 38809883, 2024). "We next assessed the predictive ability of TNFRSF4 for patient survival in neuroblastoma using both univariate and multivariate Cox regression models." (PMID 38809883, 2024). "Data generated by the Therapeutically Applicable Research to Generate Effective Treatments (TARGET) initiative phs000467 also found that TNFRSF4 was homogenously deleted in 5% of neuroblastoma cases." (PMID 38809883, 2024). "Patients with a progression event such as metastasis or relapse also exhibited significantly lower TNFRSF4 expression (N = 183), and finally, TNFRSF4 expression was significantly lower in patients who died from neuroblastoma (N = 105)." (PMID 38809883, 2024). "As TNFRSF4 displayed greater significance in Kaplan‒Meier survival analysis and because this marker has been researched more extensively in cancers outside of neuroblastoma, TNFRSF4 was selected for further studies." (PMID 38809883, 2024). "In terms of clinical outcomes, we observed that Low expression of TNFRSF4 significantly reduced survival probabilities in neuroblastoma in the SEQC cohort of 498 neuroblastomas in terms of both OS (p = 1.53e-09) and EFS (p = 4.2e-04)." (PMID 38809883, 2024). "Owing to the significant inverse correlation shown between MYCN and TNFRSF4 in multiple neuroblastoma datasets, we next aimed to examine whether TNFRSF4 could be a bonafide MYCN target." (PMID 38809883, 2024). "The SEQC dataset did not provide any information on chromosomal deletions or insertions; however, the Fischer cohort of 223 neuroblastomas did provide this information and demonstrated that TNFRSF4 expression was significantly lower in patients with a chromosome 1p deletion (N = 67, p = 9.71e-03)." (PMID 38809883, 2024). "Then, TNFRSF4 Low expression was an independent prognostic factor of survival in neuroblastoma." (PMID 38809883, 2024). "Therefore, TNFRSF4 Low expression is an independent prognostic factor of survival in neuroblastoma." (PMID 38809883, 2024). "To assess whether TNFRSF4 expression was functionally relevant important for the oncogenic capacities of neuroblastoma cells, we carried out siRNA-mediated knockdown of TNFRSF4 in Kelly (MYCN amplified) and SK-N-AS (non-MYCN amplified) neuroblastoma cells grown in vitro." (PMID 38809883, 2024).
Obesity (6 papers, 2017 to 2023). Accumulation of substantial excess body fat. "Conversely, the other TNFRSF gene members (e.g., TNFRSF4, TNFRSF9, TNFRSF14) were observed to be positively correlated with obesity in mammalian species." (PMID 35053107, 2022).
osteosarcoma (6 papers, 2021 to 2025). A usually aggressive malignant bone-forming mesenchymal neoplasm, predominantly affecting adolescents and young adults. "Our data showed that risk score exhibited a positive correlation to immune checkpoint TNFRSF4 in osteosarcoma." (PMID 35071320, 2021).
psoriasis (6 papers, 2021 to 2025). An autoimmune condition characterized by red, well-delineated plaques with silvery scales that are usually on the extensor surfaces and scalp. "As a result, immunostimulatory genes showed higher expression levels within psoriasis than normal tissues, such as CD86, CD48, TNFRSF4, TNFRSF25, ICOS, and CXCR4." (PMID 36685512, 2022).